ENSG00000277967
Gene: Miscellaneous RNA gene on chromosome 20 (49,280,485 to 49,280,571, forward strand). Ensembl gene ENSG00000277967.
Gene Ontology:
Cellular component: cytoplasm; nucleus